IL4 (interleukin 4)
Diseases named in the same sentence as IL4 in open-access papers (continued):
Sharing a sentence is not in itself a finding about the gene and the disease.
hemorrhagic fever (1 paper, 2009). An infectious disease caused by certain viruses or bacteria that can damage the walls of tiny blood vessels, making them leak, and can hamper the blood's ability to clot and cause severe, life-threatening illness. "The dengue virus, causes hemorrhagic fever and vascular lesions in humans, produces interleukin-4 (IL-4), IL-8, IL-6, IL-10, GM- colony stimulating factor (CSF), interferon-gamma (INF-gamma) and tumor necrosis factor alpha (TNF-alpha)." (PMID 19712456, 2009).
hepatotoxicity (1 paper, 2022). Toxicity that causes injury to the liver or impairs the liver function. "Some studies concluded that IL-4 plays a pathogenic role in the development of APAP-induced hepatotoxicity, but other studies have shown that transgenic C57BL/6 mice lacking IL-4 or IL-13 have increased sensitivity to AILI." (PMID 36414987, 2022).
Hernia (1 paper, 2023). "Overall, these results seem to indicate a possible mechanism for macrophage-induced hernia regression via macrophage activation and phagocytic capacity through IL4, IL17a, IL18, and RANTES and intensified tissue remodeling mediated by LIX." (PMID 37429889, 2023). "Furthermore, a possible mechanism for macrophage-induced hernia regression and tissue repair was unveiled through IL4, IL17a, IL18, LIX, and RANTES increase." (PMID 37429889, 2023).
heroin addiction (1 paper, 2020). "Our study provides evidence for the association of ADCY9, PECAM1, and IL4 with heroin addiction through stringent bioinformatics analysis." (PMID 33328875, 2020).
herpetic keratitis (1 paper, 2023). "Importantly, a previous study found that DMF improved herpetic keratitis by increasing IL-4 and IL-5 secretion, both Th2-related cytokines, by activated lymphocytes." (PMID 37371900, 2023).
Hydrocephalus (1 paper, 2023). Hydrocephalus is an active distension of the ventricular system of the brain resulting from inadequate passage of CSF from its point of production within the cerebral ventricles to its point of absorption into the systemic circulation. "This inflammatory milieu generates free radicals and pro-inflammatory cytokines such as interleukin (IL)-6, IL-4, tumor necrosis factor-α (TNFα), and transforming growth factor-β1 (TGFβ1), which contribute to the development and progression of hydrocephalus." (PMID 37794877, 2023).
Hyperammonemia (1 paper, 2016). An increased concentration of ammonia in the blood. "The levels of IL-4 were not affected by hyperammonemia (104 ± 8 % of controls) or sulforaphane (87 ± 11 %)." (PMID 26883214, 2016).
hyperprolactinemia (1 paper, 2024). Abnormally high level of prolactin in the blood. "A study recruiting 102 patients with hyperprolactinemia showed a possible autoimmune condition in which levels of interleukin-4 (IL-4) and thyroid peroxidase antibodies (TPOAb) are higher." (PMID 38529282, 2024).
hypersplenism (1 paper, 2024). Overactive functioning of the spleen, resulting in excessive destruction of blood cells. "The expression of SCARB1, ALOX15, STAT6, and IL4 was up-regulated in hypersplenism, while the PPARγ expression was down-regulated." (PMID 39620221, 2024). "In this study, the results of patients with hypersplenism showed that the c-Myc regulatory alternative activation pathway dependent genes by upregulation of IL-4 mediated signal transduction to participate in M2-like polarization and downregulation of PPARγ and IFN-γ gene expression." (PMID 39620221, 2024).
infarction (1 paper, 2020). A localised pathological necrosis of tissue resulting from obstruction of the blood supply usually by a thrombus, an embolus, or vascular torsion. "In a focal ischemia model, the administration of exogenous IL-4 improved the neurological score, increased the spontaneous polarization, reduced the infarction volume, and decreased the infiltration of macrophages/microglia, especially those with M2 phenotypes." (PMID 32982939, 2020). "However, the different effects observed in PVL models and infarction models remind us that IL-4 might play distinct roles in different diseases." (PMID 32982939, 2020).
infectious encephalitis (1 paper, 2025). An acute infectious process that affects the brain tissue. "TH2-specific interleukins (IL4 and 10) have been found to cause severe post-infectious encephalitis in mice by attenuating the TH1-cellular immune response." (PMID 40440345, 2025).
inner ear disease (1 paper, 2009). "The induction of IL1R2 by IL-4 certainly suggests that the maintenance of a TH2-like phenotype is important in controlling inner ear disease, whereas expression of IFNγ, that fosters a TH1-like response, has been observed in AIED patients, and blocks the expression of IL1R2." (PMID 19401759, 2009).
Intellectual disability (1 paper, 2011). "Elevated concentrations of IFN-γ, IL-4 and IL-5 in midgestation maternal serum were significantly associated with a 50% increased risk of ASD, regardless of ASD onset type and the presence of intellectual disability." (PMID 21810230, 2011).
irritant dermatitis (1 paper, 2025). An inflammatory skin condition caused by direct contact between the skin and an irritating substance. "In atopic and irritant dermatitis models, topical BCP suppresses keratinocyte interleukin-4 (IL-4)–driven thymic stromal lymphopoietin (TSLP) signaling and improves lesion severity." (PMID 41304852, 2025).
ischemic disease (1 paper, 2024). Lack of blood supply to an area of the body, resulting in impairment of tissue oxygenation. "More important these findings exhibit a rigid time-dependent behavior; only early-stage administration of LPS and late-stage utilization of IL-4 rouses significant therapeutic effect on ischemic disease." (PMID 39707436, 2024).
Jaundice (1 paper, 2022). Yellow pigmentation of the skin due to bilirubin, which in turn is the result of increased bilirubin concentration in the bloodstream. "Compared with BA patients with non-jaundice, the patients with jaundice had significantly increased plasma levels of 3 anti-inflammatory cytokines including IL-ra (P = 0.002), IL-4 (P = 0.010), and IL-13 (P<0.001)." (PMID 35452452, 2022).
Kaposi's sarcoma (1 paper, 2023). A malignant neoplasm characterized by a vascular proliferation which usually contains blunt endothelial cells. "Interleukin-4 (IL-4) is a tumor immunology regulator cytokine that exhibited strong anti-tumor immunity in preclinical experiments, such as the case of Kaposi sarcoma cells." (PMID 36742134, 2023).
kidney cancer (1 paper, 2023). Primary or metastatic malignant neoplasm involving the kidney. "Additionally, our research found that the interleukin-4 and interleukin-13 signalling pathways, which affect immune cell activity and are related to inflammation and kidney cancer, are enriched." (PMID 37481674, 2023).
Klebsiella Infections (1 paper, 2011). Infections with bacteria of the genus KLEBSIELLA. "In contrast, Wsh+WT+IL-4 mice recruited significantly more neutrophils than Wsh+WT controls 4 h after Klebsiella infection, as also observed in wild type Nippo mice, suggesting that IL-4 conditioning of mast cells in vivo contributes to the survival advantage in Nippo mice." (PMID 22110673, 2011).
localized scleroderma (1 paper, 2025). Localized scleroderma is the skin localized form of scleroderma characterized by fibrosis of the skin causing cutaneous plaques or strips. "Dupilumab, a monoclonal antibody targeting the α subunit of the Interleukin-4 Receptor (IL-4Rα), blocks IL-4 and IL-13 signaling and has been proposed as a potential treatment for localized scleroderma." (PMID 40816240, 2025).
lower respiratory tract infection (1 paper, 2014). "Many studies emphasized that Th2 cytokines could alter efficient Th1 antiviral immune response and lead to the development of more severe disease, but we have observed a higher IL-4 production in infants with lower respiratory tract infection." (PMID 25013801, 2014).
lupus erythematosus (1 paper, 2016). An autoimmune, connective tissue chronic inflammatory disorder affecting the skin, joints, kidneys, lungs, heart, and the peripheral blood cells. "This resonates an earlier study showing that monocytes from Lupus Erythematosus patients required more GM-CSF and IL-4 to obtain viable DC." (PMID 27846835, 2016).
Lymphomatoid Papulosis (1 paper, 2014). A chronic, recurrent cutaneous disorder characterized by the presence of spontaneously regressing papules. "Although the role of IL-4 in eosinophil recruitment is controversial, IL-4 is highly expressed by T cytotoxic 2 cells, with abundant background eosinophils, in CD8+ lymphomatoid papulosis." (PMID 25273521, 2014).
lymphoproliferative disorders (1 paper, 2013). "Moreover, cytokines (such as APRIL) produced by neutrophils in patients with lymphoproliferative disorders increase tumor aggressiveness, while others (i.e. IFN-γ, -α, IL-4, -8) can inhibit apoptosis of malignant B cells in vitro." (PMID 24155890, 2013).
macular degeneration (1 paper, 2022). Loss of vision in the central portion of the retina (macula), secondary to retinal degeneration. "The violin plot data showed that IL-4 was mainly enriched in immune cells and was particular decreased in the sample from macular degeneration patients." (PMID 36539414, 2022).
meningoencephalitis (1 paper, 2020). Inflammation of the meninges and brain, generally secondary to an infectious cause. "Studies have shown that expression of CD40-ligand on activated T cells and interleukin 4 (IL-4) production are significantly lower in EV-A71 infected children with meningoencephalitis than those without it." (PMID 32153545, 2020).
microphthalmia (1 paper, 2019). Congenital or developmental anomaly in which the eyeballs are abnormally small. "We identified motifs associated with the EGR family of TFs in EC1 (late responsive IL-4 clusters) and the Microphthalmia-associated (MAF) TF family in EC2 and EC3 (early and intermediate responsive IL-4 clusters), as proposed by recent studies, as well as MITF and RUNX under the IL-4 specific ECs." (PMID 30799488, 2019).
morbid obesity (1 paper, 2024). An excess of body weight, normally defined as an individual with a body mass index greater than 35 or a body weight greater than one hundred percent of ideal body weight. "The multiple linear regression model results reveal a significant relationship between hepatic levels of ACE and the cytokines IL-4 and IL-13 in patients with morbid obesity and MASLD." (PMID 39337863, 2024).
multiple system atrophy (1 paper, 2024). Multiple system atrophy (MSA) is a neurodegenerative disorder characterized by autonomic failure (cardiovascular and/or urinary), parkinsonism, cerebellar impairment and corticospinal signs with a median survival of 6-9 years. "Other works revealed increased levels of interferon γ, IL-10, IL-18, IL-1β, IL-4, IL-6, transforming growth factor β1, and Tumor Necrosis Factor-α in PSP and Multiple System Atrophy when compared to PD." (PMID 39176092, 2024).
muscle disorders (1 paper, 2023). "Since impairment of myoblast fusion causes several muscle disorders, the IL-4/IL-4Rα axis can be a potential therapeutic target for the treatment of muscular pathologies." (PMID 37174683, 2023).
myelodysplastic syndrome (1 paper, 2012). A clonal hematopoietic disorder characterized by dysplasia and ineffective hematopoiesis in one or more of the hematopoietic cell lines. "Hence, in absence of Th-2 cytokines (IL-4 and IL-5), cytokine imbalances associated with exaggerated Th-1 cytokines may occur in a subset of 5q minus myelodysplastic syndrome." (PMID 22934211, 2012). "Due to the absence of Th-2 cytokines, such as IL-4 and IL-5, in a subset of 5q minus myelodysplastic syndrome, proinflammatory Th-1 cytokines such as IFN-γ and TNF-α may be exaggerated in an environment conducive to antigen expression." (PMID 22934211, 2012).
myelofibrosis (1 paper, 2025). A partial or complete replacement of the bone marrow stroma by fibrous tissue. "We identified a set of inflammatory cytokines, including IL-1alpha, IL-4, IL-6, IL-7, IL-9, IL-15 and TNF-alpha, which are elevated in the serum of JAK2V617F mice, similar to the alterations in circulating cytokines observed in patients with myelofibrosis." (PMID 40386398, 2025).
Myelopathy (1 paper, 2017). Myelopathy is an descriptive term, referring to pathology leading to a neurologic deficit related to the spinal cord. "Pro-inflammatory cytokines (Th1) are involved in the progression of myelopathy and IFN-γ downregulates the production of IL-4 by Th2 cells." (PMID 28376092, 2017).
myocardial disease (1 paper, 2017). "The role of IL‐4 and IL‐13 signaling in myocardial disease has been controversial." (PMID 28528324, 2017).
Neonatal sepsis (1 paper, 2017). Systemic inflammatory response to infection in newborn babies. "In the present study, serum levels of the proinflammatory cytokines TNF-α, IL1-β, and IL-6 and the anti-inflammatory cytokines IL-4 and IL-10 were evaluated for 25 subjects with neonatal sepsis." (PMID 28367457, 2017).
nephrotoxicity (1 paper, 2024). Toxicity that causes injury to the kidney or damages its function. "Pioglitazone reduced the mRNA levels of pro-inflammatory cytokines (IL-6 and TNF-α) and increased the mRNA levels of anti-inflammatory cytokines (IL-4 and IL-10) in an in vitro model of calcium oxalate monohydrate-induced nephrotoxicity." (PMID 39621679, 2024).
neuroborreliosis (1 paper, 2015). "In this population of individuals, suffering from neuroborreliosis, IFN-γ production was significantly increased while IL-4 production was unusually low." (PMID 26697208, 2015).
Neurodevelopmental delay (1 paper, 2020). "For controls, we found higher average levels of a subset of cytokines including IL-4, IL-1β, PlGF, GM-CSF, SAA, IL-15, TNF-β, VEGF-D, IL-12p70, Tie-2, IL-2, IL-17α, IFN-ɣ, and IL-10 in children with neurodevelopmental delay (C/ND), compared to that of their typically developing (C/TD) counterparts." (PMID 31992316, 2020).
Neurofibrillary tangles (1 paper, 2020). Pathological protein aggregates formed by hyperphosphorylation of a microtubule-associated protein known as tau, causing it to aggregate in an insoluble form. "However, there was a trend toward decrease in the PHF1 epitope after IL-4 injection (P = 0.1), which identifies the late-stage neurofibrillary tangle (NFT) phospho-tau sites Ser396 and Ser404." (PMID 32528242, 2020).
neurofibroma (1 paper, 2021). An intraneural or extraneural neoplasm arising from nerve tissues and neural sheaths. "In regard to NF1, we hypothesize that anti-IL-4 receptor monoclonal antibody dupilumab may inhibit the growth of neurofibromas, interfering with IL-4 and IL-13 binding to type I and type II receptors expressed on mast cells and fibroblasts." (PMID 34275694, 2021).
neuroma (1 paper, 2022). A tumor that grows from a nerve or is composed of nerve cells and nerve fibers. "Compared with neuroma cell cultured alone, secretions of M1 macrophage-inducible factors, such as IFN-γ and TGF-ß, were increased after adding the HuD protein, while the secretions of M2 macrophage-inducible factors, such as IL-4 and Arg-1, were decreased." (PMID 35294333, 2022).
neuromyelitis optica (1 paper, 2024). A rare inflammatory disease of the central nervous system characterized mainly by attacks of uni- or bilateral optic neuritis (ON) and acute myelitis. "In humans, it has been suggested an increased MS susceptibility based on IL4 gene polymorphism and elevated serum level of IL-4 in neuromyelitis optica and MS, but without any significant difference between them." (PMID 38263055, 2024).
neuroschistosomiasis (1 paper, 2024). Schistosomiasis of the brain, spinal cord, or meninges caused by infections with trematodes of the genus schistosoma (primarily schistosoma japonicum; schistosoma mansoni; and schistosoma haematobium in humans). "In the present study, the predominant production of TNFα over type 2 cytokines (IL-4 and IL-13) could suggest the domination of pro-inflammatory effects of TNFα during neuroschistosomiasis after 8 weeks post-infections." (PMID 39959586, 2024).
nosocomial infection (1 paper, 2014). An infection acquired in a hospital or other healthcare setting. "Among septic shock children, those who went on to develop persistent or nosocomial infection had decreased T-cell ex vivo PHA-induced production of IFN-γ (P = 0.01), IL-2 (P = 0.01), IL-4 (P = 0.008), and IL-10 (P = 0.001) compared with septic shock children who did not." (PMID 25005517, 2014).
ocular sarcoidosis (1 paper, 2022). A leading cause of inflammatory eye disease is sarcoidosis. "A study that compared the vitreous concentrations of inflammatory cytokines between PDR and ocular sarcoidosis reported that IL-4, IL-17A, IL-31, and TNFα were significantly elevated in PDR, indicating the involvement of Th2 and Th17-related immune responses in the pathogenesis of PDR." (PMID 35806888, 2022).
oligoarticular JIA (1 paper, 2020). "Children with oligoarticular JIA have polarized synovial fluid monocytes of a specific M1(IFNγ)/M2(IL-4)-like pattern." (PMID 32787920, 2020).
oral disease (1 paper, 2019). "Interferon (IFN)-γ, IL-4, IL-6, IL-8, regulated on activation-normal T cell expressed and secreted (RANTES), stem cell factor (SCF), and monocyte chemoattractant protein (MCP) -1 were significantly lower on day 6 than on day 0 in cats with severe oral disease." (PMID 30822336, 2019).
oropharyngeal squamous cell carcinoma (1 paper, 2020). "Finally, analyses of surgical specimens of oropharyngeal squamous cell carcinoma indicated that high IFN-γ and low IL-4, low TSLP, and low TGFβ expression was associated with better prognosis in oropharyngeal squamous cell carcinoma patients." (PMID 33042121, 2020).
Pain (1 paper, 2025). An unpleasant sensory and emotional experience associated with actual or potential tissue damage, or described in terms of such damage. "The most relevant cytokines observed in PTX-induced neuropathic pain are IL-1β, IL-8, and TNF-α, as well as IL-6, IL-4, and IL-10." (PMID 40006070, 2025).
paraneoplastic neurological syndromes (1 paper, 2019). "The purpose of our study was to examine serum markers of BBB breakdown and serum concentrations of proinflammatory (TNF-alpha, VEGF) and anti-inflammatory/immunosuppressive (IL-4) cytokines in patients with paraneoplastic neurological syndromes." (PMID 30374596, 2019).
Peptic ulcer (1 paper, 2025). The term peptic ulcer refers to acid peptic injury of the digestive tract, resulting in mucosal break reaching the submucosa. "A decrease in IL-1β and IFN-γ levels combined with an increase in IL-4 levels indicates its potent anti-inflammatory effect, which probably plays a key role in preventing peptic ulcer relapses." (PMID 40283939, 2025).
Periportal fibrosis (1 paper, 2021). The presence of fibrosis affecting the interlobular stroma of liver. "The present study demonstrates a greater production of IL-4, IL-5, and IL-13 by the lymphocytes of individuals with periportal fibrosis." (PMID 33692784, 2021). "As has already been described in the literature, we found an increase of the Th2 cytokines IL-4, IL-5, and IL-13 in the group with periportal fibrosis." (PMID 33692784, 2021).
PFAPA (1 paper, 2024). "Thus, it can be concluded that further research is needed to question the relationships between Treg and IL-4 in the coexistence of PFAPA and SIgAD." (PMID 39119144, 2024).
pinworm infection (1 paper, 2017). "The amount of fecal IL-1ß and IL-4 were similar before and after pinworm infection." (PMID 28945752, 2017).